ORAI3 (ORAI calcium release-activated calcium modulator 3)
Diseases named in the same sentence as ORAI3 in open-access papers (continued):
Sharing a sentence is not in itself a finding about the gene and the disease.
pulmonary fibrosis (2 papers, 2022 to 2025). Chronic progressive interstitial lung disorder characterized by the replacement of the lung tissue by connective tissue, leading to progressive dyspnea, respiratory failure, or right heart failure. "These suggest that Orai3 was implicated in the promotion of pulmonary fibrosis." (PMID 36128650, 2022). "In this study, we found that Orai3 expression was increased significantly in BLM‐induced lung fibrosis." (PMID 36128650, 2022). "Our results revealed a new mechanism by which Orai3‐Orai1 heteromultimeric channels activates fibroblasts to develop pulmonary fibrosis." (PMID 36128650, 2022). "But the roles of Orai3 have less attention on the mechanism of regulating lung fibrosis." (PMID 36128650, 2022). "In our results, elevated levels of Orai3 were observed in lung fibrosis model in vivo and vitro." (PMID 36128650, 2022). "That may establish a pro‐fibrotic role for the Orai3 and a mechanism via SEPTIN4 regulating Orai channel remodelling in pulmonary fibrosis." (PMID 36128650, 2022).
pulmonary hypertension (2 papers, 2018 to 2021). Increased pressure within the pulmonary circulation due to lung or heart disorder. "In addition, this can stimulate Stim1-independent Ca2+ entry through Orai3, limiting, in this way, the regression of pulmonary hypertension." (PMID 35082688, 2021). "Orai1, Orai12, and Orai3 can promote SOCE in PASMCs and may serve as potential therapeutic targets for chronic hypoxia-induced pulmonary hypertension." (PMID 30320134, 2018).
acinar adenocarcinoma (1 paper, 2016). "The staining of Orai3 was low in non-tumour lung, and in invasive predominant lepidic and papillary adenocarcinoma, was moderate in infiltrating acinar adenocarcinoma, and high in infiltrating solid adenocarcinoma." (PMID 27835593, 2016).
atopic asthma (1 paper, 2021). An asthma that is characterized by symptoms that are triggered by an allergic reaction caused by inhaled allergens such as dust mite allergen, pet dander, pollen and mold. "The expression of ORAI3 proteins has been linked to vascular and airway pathologies, including restenosis, hypertension, and atopic asthma." (PMID 34926685, 2021).
colorectal adenocarcinoma (1 paper, 2024). The most common type of colorectal carcinoma. "By contrast, our results indicate that treatment of the colorectal adenocarcinoma cell lines with postbiotics of Lacticaseibacillus paracasei and Lactiplantibacillus plantarum did not significantly alter the protein content of Orai3 and STIM2." (PMID 38514909, 2024).
colorectal cancer (1 paper, 2021). A primary or metastatic malignant neoplasm that affects the colon or rectum. "In the human colorectal cancer cell line HT29, the expression of Orai3, as well as Orai1, Orai2, STIM1, and TRPC1 has been shown to be enhanced as compared to the normal human colon mucosal epithelial cell line NCM460, whereas STIM2 expression was downregulated in cancer cells." (PMID 34768857, 2021).
coronary artery disease (1 paper, 2015). "The data suggest that Orai3 is a significant contributor to VEGF signaling in several important vascular settings: macrovascular as well as microvascular, and in patients with coronary artery disease and cancer." (PMID 26160956, 2015).
dysplasia (1 paper, 2023). A usually neoplastic transformation of the cell, associated with altered architectural tissue patterns. "To investigate the role of Orai3 in oral carcinogenesis, we determined the transcript level of Orai3 in normal human oral epithelia (NHOE), dysplasia, and OSCC tissues by employing laser capture microdissection (LCM), followed by qPCR." (PMID 37759448, 2023).
erectile dysfunction (1 paper, 2022). Persistent or recurrent inability to achieve or to maintain an erection during sexual activity. "Furthermore, we previously reported that Orai3 was overexpressed in the human corpus cavernosum in physiologic aging, while both Orai1 and Orai3 were upregulated in the cavernosal tissue from men with erectile dysfunction." (PMID 36429103, 2022).
fibrosis (1 paper, 2022). the formation of excess fibrous connective tissue in an organ or tissue in a reparative or reactive process. "For our research, Orai3 interacted with Orai1 was significantly increased in lung from BLM‐induced fibrosis rat and fibroblast with TGF‐β1 treatment." (PMID 36128650, 2022).
gout (1 paper, 2021). A condition characterized by painful swelling of the joints, which is caused by deposition of urate crystals. "To determine whether the increase in ORAI3 transcripts is disease-specific, we profiled naive CD4+ T cells from patients with gout, systemic lupus erythematosus (SLE), and PsA for the expression of ORAI3." (PMID 33568645, 2021). "ORAI3 transcription was also increased in PsA, albeit not to the same extent as in RA, while the number of transcripts in naive CD4+ T cells from patients with SLE or gout were not different from those from HCs." (PMID 33568645, 2021).
Hypertension (1 paper, 2021). The presence of chronic increased pressure in the systemic arterial system. "Besides, downregulated ORAI3 is associated with the changes in cerebrovascular contractile responses in high-salt intake-induced hypertension." (PMID 34926685, 2021).
injury (1 paper, 2023). Damage inflicted on the body as the direct or indirect result of an external force, with or without disruption of structural continuity. "We next explored the role of Orai3 and Orai3-mediated store-operated Ca2+ entry (SOCE) in radiation-induced brain injury." (PMID 37047790, 2023).
melanoma (1 paper, 2014). A malignant, usually aggressive tumor composed of atypical, neoplastic melanocytes. "In contrast, STIM2, Orai2 and Orai3 expression was undetectable or barely detectable in the melanoma cell lines (data not shown)." (PMID 24586666, 2014).
pancreatic ductal adenocarcinoma (1 paper, 2022). An infiltrating adenocarcinoma that arises from the epithelial cells of the pancreas. "In pancreatic ductal adenocarcinoma, Orai3 knock-down resulted in decreased cell proliferation due to a halted cell cycle in the G2/M-phase; however, the underlying mechanism for Orai3-dependent cell cycle regulation is unknown." (PMID 36612099, 2022).
prostate adenocarcinoma (1 paper, 2024). "In an aged knock-in mouse prostate adenocarcinoma model, ORAI3 and STIM2 mRNA levels were significantly increased compared to ORAI1 and STIM1, and ORAI3–STIM2 interaction was detected in PC–3 cells under basal conditions." (PMID 38672434, 2024).
staphylococcal infection (1 paper, 2019). An infection caused by Staphylococcus. "The potential importance of ORAI3 in the context of external stress responses is also reflected in the increased expression of ORAI3 in the lungs of mice after staphylococcal infection, where the reduced sensitivity of ORAI3 to ROS-mediated inhibition may be important in immune responses." (PMID 30754719, 2019).
tongue cancer (1 paper, 2023). A malignant neoplasm affecting the tongue. "To further substantiate the significance of the elevated Orai3 level in the context of oral carcinogenesis, we employed a mouse model of tongue cancer induced by carcinogens." (PMID 37759448, 2023). "Moreover, Orai3 expression was greatly elevated in a carcinogen-induced tongue cancer mouse model." (PMID 37759448, 2023).
type 1 diabetes (1 paper, 2018). "Similar to the expression in PBMCs from pregnant women, the average expression level of ORAI1, ORAI2 and ORAI3 were significantly up-regulated by type 1 diabetes." (PMID 30543678, 2018).
cancer (43 papers, 2013 to 2026). A tumor composed of atypical neoplastic, often pleomorphic cells that invade other tissues. "Dysregulation in Orai channels in particular Orai3 expression and function is associated with various types of cancer." (PMID 41023307, 2025). "Evidence suggests that ORAI3 governs PCa by creating either ARC channels or LRC channels, even through ORAI3-encoded SOCs in malignant cells instead of healthy cells, which controls cancer hallmarks and promotes carcinogenesis." (PMID 38672434, 2024). "This is due to either altered expression of CRAC channel proteins, specifically, STIM1/STIM2, Orai1, and Orai3 in cancer cells compared with healthy cells or mutations in STIM1 or Orai1 proteins." (PMID 36612099, 2022). "Orai3 overexpression is associated with supporting several cancer hallmarks, including cell cycle progression, proliferation, migration, and apoptosis resistance." (PMID 34768857, 2021). "Overexpression of functional Orai3 has been reported in several neoplastic cells where this channel has been associated to the development or support of several cellular activities, thus leading to cancer progression." (PMID 34768857, 2021). "Collectively, elevated expression of both ORAI1 and ORAI3 underpins cancer hallmarks across diverse tumor types, positioning them as prognostic indicators and actionable therapeutic targets in malignancies, including lung cancer." (PMID 41596760, 2026). "The top three genes with the highest AUC values (ORAI3, BCAM, and ATP6V0A1) have been associated with cancer development." (PMID 38256136, 2024). "Recently, more and more evidence is indicating that Orai1′s two homologs, Orai2 and Orai3, play a role in the development of different types of cancer such as lung, breast, prostate, and leukaemia." (PMID 37259313, 2023). "This suggests that the Orai3/ID1 axis is a novel regulatory signaling mechanism for maintaining cancer stemness in OSCC." (PMID 37759448, 2023). "This underscores an innovative regulatory mechanism for cancer stem cells involving the Orai3/ID1 axis." (PMID 37759448, 2023). "Orai3 is induced by hypoxic environments in some cancer cells, for example, the induction of Orai3 under hypoxia is mediated by HIF-1α in the TNBC MDA-MB-468 cell line, increasing the TRPC1 ion channel induced by HIF-1α." (PMID 37833987, 2023). "In alignment with our observations in human cancer cases, a significant increase in Orai3 expression was evident in the tongues bearing tumors compared to the tongues with a normal status." (PMID 37759448, 2023). "Orai3 is a calcium channel activated by Stim1 or Stim2,9 but in further studies, Orai3 interacted with Orai1 to form a heteromer was recognized in cancer cells for proliferation and decreased apoptosis." (PMID 36128650, 2022). "In some cancer types, Orai3 and/or STIM2 expression exerts pro-proliferative effects by influencing the cell cycle via various signaling cascades." (PMID 36612099, 2022). "A number of cancer hallmarks are supported by overexpression of ORAI3, including cell cycle progression, proliferation, migration, and resistance to apoptosis." (PMID 36588677, 2022). "In other cancer types, enhanced Orai3 expression increased Orai1/Orai3 heteromeric formation and thus reduced the number of functional Orai1 channels." (PMID 36612099, 2022). "A shift in the Orai1:Orai3 expression ratio increases SOCE, as well as the levels of cancer stem cell markers, a mechanism potentially linked to the PI3K/Akt pathway." (PMID 36612099, 2022). "This particular isoform-specific role of Orai3 in different cancers together with isoform-specific features and functionality provides the opportunity for more targeted therapeutic developments." (PMID 36612099, 2022). "Another study suggested heteromeric Orai1/Orai3 channel formation, whereby Orai3 expression is downregulated in cancer, thus altering the Orai1/Orai3 ratio." (PMID 36612099, 2022).
cancer (continued). "The variation in the expression of Orai1 and Orai3 upon the treatment with chemotherapeutic drugs has been reported in several cancer types." (PMID 34065942, 2021). "Secondly, our in vivo analysis of MMP2, a critical regulator of cancer cell invasion and metastasis, shows that Orai3 knockdown decreases the expression of MMP2." (PMID 34885048, 2021). "It has been reported that the progressive development of cancer cells is connected to an increase in Orai3 expression." (PMID 34360783, 2021). "To summarize, Orai3 expression and function have been reported to be remodeled in different cancer cells." (PMID 34768857, 2021). "An increasing number of reports demonstrates a unique and predominant role of Orai3 in cancer development among all three Orai channel family members." (PMID 34360783, 2021). "Taking into consideration that cancer cell lines have been the most frequently used method to study lung CSCSs so far, we decided to investigate the Orai3 channel in sorted CD133+ cells." (PMID 34065942, 2021). "Especially Orai3 seems to be a major contributor to the development of various types of cancers and Orai2 has been identified to fine-tune immune cell response." (PMID 34360783, 2021). "Definitely, further studies are required for comprehensively delineating the molecular choreography that connects Orai3 to cancer metastasis in general and PC progression in particular." (PMID 34885048, 2021). "This review summarizes the current knowledge concerning the functional role of Orai3 in the pathogenesis of cancer." (PMID 34768857, 2021). "An important point is that Orai3 is overexpressed in all these cancers (cancerous cells used in the in vivo studies) and Orai3 silencing in these cells leads to a decrease in their tumorigenic potential." (PMID 34885048, 2021). "In the present study, we aimed to investigate the functional role of Orai3 in resistance to CDDP through the regulation of cancer stem cells markers expression." (PMID 34065942, 2021). "This unprecedented functional role of Orai3 has a significant effect on the biology of these cancer cells, where Orai3 plays a relevant role in cell cycle progression, cell proliferation, and apoptosis resistance." (PMID 34768857, 2021). "Similar observations have been made in prostate cancer where Orai3 overexpression is positively correlated with aggressive cancer phenotypes and poor clinical prognosis." (PMID 32575381, 2020). "Store-operated heteromeric Orai1/Orai3 channels have been discussed in the context of aging, cancer, and immune cell differentiation." (PMID 32252254, 2020). "Increased expression of ORAI3 proteins found in cancer cells over normal cells was observed, and experimentally reducing the expression of ORAI3 inhibited cell proliferation and cell viability in cancer cells but not normal cells." (PMID 33569087, 2020). "Studies assessing ORAI3 have highlighted the potential importance of ORAI3 in specific cancer types." (PMID 30754719, 2019). "Not only immune cells but also cancer cells change the Orai3 to Orai1 ratio, thereby changing the H2O2 dependence of Orai-based Ca2+ entry." (PMID 30935064, 2019). "We focussed on mCRC cells for the following reasons: 1) metastasis is the leading reason for mortality in cancer patients and 2) Stim1 and Orai3 proteins were up-regulated in mCRC cells." (PMID 30123430, 2018). "Specifically, the dysregulation of distinct molecular components of SOCE, especially the STIM1 and Orai1 proteins and their homologues STIM2, Orai2, and Orai3, plays important roles in the pathophysiology of different types of cancer." (PMID 29951353, 2017). "As Orai3 confers survival of cancer cells, we evaluated the expression of Orai3 in stage Ib and II-III." (PMID 27835593, 2016). "Recently, compelling evidence has suggested that ORAI3 is closely related with c-Myc, which is a key proto-oncogene and is enhanced in most human cancers." (PMID 27013185, 2016).
cancer (continued). "We have previously reported that down-regulation of Orai3 inhibits cancer cell proliferation, contributes to cell cycle arrest in G1 phase, and increases apoptotic cell death." (PMID 24058448, 2013). "Moreover, ORAI3 enrichment sustains cancer stem cell traits and platinum resistance in NSCLC, whereas its pharmacological or genetic silencing restores chemosensitivity and reduces stemness markers." (PMID 41596760, 2026). "Orai3 overexpression is well-documented in other types of cancers as well but the molecular players and signaling modules driving Orai3 regulation are still unknown." (PMID 41023307, 2025). "Interestingly, our pilot studies suggest that there are epigenetic changes in the Orai3 promoter during cancer progression." (PMID 41023307, 2025). "Moreover, the Ca2+-independent mechanism of Orai3 was reported in cancer, which adds an additional layer of interest for the future study of Orai3." (PMID 37759448, 2023). "Orai3 regulates cancer growth and migration through multiple pathways." (PMID 37759448, 2023). "Collectively, our data suggest that Orai3 promotes OSCC progression by increasing cancer stemness." (PMID 37759448, 2023). "Additionally, we have furnished compelling evidence that Orai3 significantly advances the progression of OSCC by amplifying cancer stemness through the elevation of ID1 expression." (PMID 37759448, 2023). "Therefore, taken together, our data clearly suggest that Orai3 regulates the integral components of cancer metastasis such as cell migration, invasion and EMT." (PMID 34885048, 2021). "The potential role of the Orai3 modulators in cancer therapy deserves further study." (PMID 34768857, 2021). "In addition to their implication in different physiological processes, Orai2 and Orai3 are also involved in a variety of pathophysiological events, including cancer." (PMID 35008277, 2021). "Like Orai1, upregulated Orai3 has been reported in many cancers." (PMID 32575381, 2020). "In this case, ORAI3 upregulation might offer the cancer cells a survival advantage by contributing to SOCE-mediated signaling, while limiting SOCE-mediated toxicity." (PMID 32415068, 2020). "However, the ability of ORAI3 but not ORAI1 silencing to attenuate EGFR phosphorylation induced by hypoxia suggested that specific events in cancer cells activated by hypoxia are fine-tuned by ORAI3." (PMID 30754719, 2019). "Thus, higher ROS levels in this case would be considered pro-tumorigenic, whereas in case the Orai3–Orai1 ratio is low and where mostly Orai1 homomultimers are formed, ROS levels would be considered anti-tumorigenic, resulting finally in cancer cell death." (PMID 30935064, 2019). "In contrast, fewer studies have assessed its related isoform ORAI3 in cancer." (PMID 30754719, 2019). "Of note, Orai3 may replace Orai1 as the pore-forming subunit of store-operated channels in cancer cells and could, therefore, emerge as a promising target for anti-cancer therapies." (PMID 29324706, 2018). "It is therefore possible that different ion channels could be involved in affecting specific SOCE profiles as TRPC, Orai1 and STIM1 that can form heteromeric complexes or other members of the TRPC or ORAI families such as Orai3 in cancer cells." (PMID 23700407, 2013). "However in these cases, the development of cancer (mammary tissue/cell lines) or subjection of cells to oxidative stress (effector TH cells) resulted in upregulation of Orai3 expression." (PMID 24040356, 2013). "Consequently, we hypothesize that Orai3 contributes to cancer stemness through the elevation of ID1 expression." (PMID 37759448, 2023). "In particular, STIM2 or Orai3 may function as a therapeutic target for selective cancer therapy." (PMID 36612099, 2022). "Moreover, especially Orai3 has been identified to initiate cancer cell development." (PMID 34360783, 2021).